RASL10B (RAS like family 10 member B)
Description:
May facilitate the release of atrial natriuretic peptide by cardiomyocytes and hence play a role in the regulation of arterial pressure.
Synonyms: RRP17; VTS58635
Tractability: Antibody: UniProt places it where antibodies can reach, with high confidence; its Gene Ontology location is reachable by antibodies, with medium confidence.
Gene: Protein-coding gene on chromosome 17 (35,731,639 to 35,743,521, forward strand). Ensembl gene ENSG00000270885.
Subcellular location: Cell membrane
Subcellular location (Human Protein Atlas): Vesicles
Gene Ontology:
Molecular function: protein binding; GTPase activity; G protein activity; GTP binding
Biological process: positive regulation of peptide hormone secretion; regulation of systemic arterial blood pressure by atrial natriuretic peptide
Cellular component: plasma membrane
Genetic constraint (gnomAD): Loss-of-function variants: 10 observed, 21.44 expected, observed/expected ratio (o/e) 0.47, 90% interval 0.29 to 0.79. The upper end of that interval is the gene's LOEUF score, 0.79, which puts it in group 3 of 6, group 1 being the genes least tolerant of losing a copy. Missense variants: 231 observed, 304.09 expected, observed/expected ratio (o/e) 0.76, 90% interval 0.68 to 0.85. Synonymous variants: 110 observed, 123.05 expected, observed/expected ratio (o/e) 0.89, 90% interval 0.76 to 1.05.
Homologues: Orthologues: rabbit RASL10B (100% identical), chimpanzee RASL10B (99% identical), macaque RASL10B (99% identical), rat Rasl10b (99% identical), mouse Rasl10b (99% identical), pig RASL10B (99% identical), dog RASL10B (99% identical), guinea pig RASL10B (99% identical), tropical clawed frog rasl10b (88% identical), zebrafish RASL10B (40% identical). Paralogues in human: RASL10A (52% identical), DIRAS2 (33% identical), RASD2 (32% identical), RASD1 (31% identical), DIRAS1 (29% identical), RAP2B (26% identical), DIRAS3 (25% identical), RAP1B (25% identical), RAP2A (25% identical), RALB (25% identical), RAP1A (25% identical), RRAS2 (25% identical), and 23 more.
Diseases named in the same sentence as RASL10B in open-access papers:
RASL10B is named in the same sentence as 9 diseases in open-access papers, as found by Europe PMC text mining. Sharing a sentence is not in itself a finding about the gene and the disease. The quoted sentences say what the papers report.
breast carcinoma (2 papers, 2023 to 2025). "RASL10B is a widely expressed, cytoplasmic Ras-like small GTPase whose mRNA is downregulated in breast cancer cells." (PMID 41562091, 2025).
adenoma (1 paper, 2025). A neoplasm arising from the epithelium. "RASL10B is methylated in sessile serrated adenoma/polyp (SSA/P) and cancer in SSA/P." (PMID 41562091, 2025).
colon cancer (1 paper, 2025). "An 11-gene signature, including RASL10B, predicted poorer survival in colon cancer." (PMID 41562091, 2025).
colorectal cancer (1 paper, 2021). A primary or metastatic malignant neoplasm that affects the colon or rectum. "The subnetworks revealed genes that are previously reported as CRC-associated as well as several yet undeciphered genes that may contribute colorectal cancer, such as DNAAF5, RASL10B, DUSP19, and TTC27." (PMID 34790220, 2021).
lymphoma (1 paper, 2025). A malignant (clonal) proliferation of B- lymphocytes or T- lymphocytes which involves the lymph nodes, bone marrow and/or extranodal sites. "In pancreatic ductal adenocarcinoma, increased miR-184 promotes apoptosis via caspase-3/9 activation and Bcl-2 downregulation, while lymphomas show suppression through inhibition of RasL10B, TNFAIP8, and iASPP, promoting apoptosis." (PMID 41379397, 2025).
tumor (5 papers, 2016 to 2025). "Likewise, the up-regulated Rasl10b gene encoding a small GTPase with tumour suppressor potential, which was shown to regulate blood flow in the atrium, could also participate in the antitumoral response downstream of oxaliplatin." (PMID 39578077, 2025). "However, evidence that RASL12 functions as a small GTP-binding protein is lacking; In fact, studies have reported that RASL12 could be homologous to the RAS-like GTPases RERG, RASL11A, RASL11B, RASL10A and RASL10B, which play tumor-suppressive roles in human cancers." (PMID 34819106, 2021). "Among them, we selected five decreased (CCDC28B, SREK1IP1/P18SRP/SFRS12IP1, RASL10B, PHF21A/BHC80 and PGC) and two increased genes (IL-11 and CXCL2), by microarray, as differentiation-, splicing-, inflammation-, or tumor-related genes." (PMID 26701885, 2016).
RASL10B also shares sentences with these, for which no sentence is quoted: cancer (2 papers); MALT lymphoma (1); pancreatic ductal adenocarcinoma (1).